RCAN1 (regulator of calcineurin 1)
Diseases named in the same sentence as RCAN1 in open-access papers (continued):
Sharing a sentence is not in itself a finding about the gene and the disease.
tumor (33 papers, 2009 to 2026). "As expected, mice implanted with RCAN1-4pos GBM cells exhibited continued tumor growth when receiving control treatment (mock-T cells or PBS)." (PMID 41436600, 2026). "Correspondingly, we observed significant HLA-I-dependent tumor killing by LDH assay upon coculturing RCAN1-422-32-primed CD8+ T cells with SF10360 (RCAN1-4pos GBM cells)." (PMID 41436600, 2026). "In coculture assays with T cells from patient PBMCs, T cells from HLA-A24+ patients exhibited increased tumor cell killing ability when cultured with RCAN1-4pos KNS-42 cells compared with RCAN1-4KO KNS-42 cells (fold change >1)." (PMID 41436600, 2026). "Functional studies of TCR-Ts demonstrated the in vitro and in vivo killing of RCAN1-4pos GBM tumor cells, highlighting its potential as an immunotherapeutic target in mesenchymal GBM." (PMID 41436600, 2026). "T cells from HLA-A24− patients killed similar numbers of tumor cells when cultured with RCAN1-4pos KNS-42 cells or RCAN1-4KO KNS-42 cells (fold change = 1)." (PMID 41436600, 2026). "A nomogram based on RCAN1.2 expression, tumor stage, LNM and patients' age presented good performance to predict 2-year and 5-year survival probability." (PMID 37576400, 2023). "The mRNA expression of three RCAN1 isoforms was detected in paired tumor and normal tissues from 100 ESCC patients by real-time PCR." (PMID 37576400, 2023). "Compared to the paired normal tissues, RCAN1 isoform 1 (RCAN1.1, P=0.0027) and RCAN1 isoform 2 (RCAN1.2, P=0.0006) were significantly decreased in tumor tissues." (PMID 37576400, 2023). "The concordance index of nomogram to predict OS was 0.693 based on LNM, RCAN1.2, tumor stage and patients' age." (PMID 37576400, 2023). "The biphasic role of RCAN1, its characteristics as both tumor inhibitor and tumor promoter, mean that RCAN1 is highly expressed in some tumors." (PMID 35717152, 2022). "Except for hypopharyngeal and laryngopharynx cancer, high expression of RCAN1 inhibits tumor progression." (PMID 35717152, 2022). "In lung cancer, RCAN1 inhibits tumor proliferation, angiogenesis, and metastases by inhibiting the CN-NFAT pathway." (PMID 35717152, 2022). "RCAN1 (or RCAN1.4) is a metastasis suppressor, having inhibitory tumor growth and metastasis effects in vitro and in vivo." (PMID 35717152, 2022). "In accordance with these reports, the overexpression of RCAN1 using adenovirus inhibited NF-κB and suppressed xenografted tumor growth in a severe combined immunodeficiency (SCID) model." (PMID 35204088, 2022). "The increased RCAN1 expression is associated with a lower tumor stage in KIRC, KIRP, LIHC, THCA, and uterine corpus endometrial carcinoma (UCEC) and a higher tumor stage in BLCA." (PMID 35717152, 2022). "Firstly, previous studies have shown that increased RCAN1 overexpression promotes apoptosis by mediating caspase-3/caspase-9 expression, which is independent of CN and is a possible mechanism for inhibiting tumor growth." (PMID 35717152, 2022). "Our results are the first time to report the correlation between RCAN1.4 and tumor immune environment, especially T cells." (PMID 33824473, 2021). "For example, RCAN1 elevation promotes AD pathogenesis, while increased RCAN1 suppresses tumor growth." (PMID 29416595, 2018). "Further, Rcan1 decreased tumor growth in the xenografts into a trisomic background due to effects on angiogenesis, proliferation and/or apoptosis depending on the tumor cell lines used for transplant." (PMID 26752700, 2016). "By contrast, a uniformed RCAN1 staining pattern was observed in most tumor cells, specifically the spindle-shaped endothelial cells." (PMID 25811856, 2015). "The log rank test showed that the tumor growth in RCAN1 overexpressed group is slower than the control (P=0.015)." (PMID 26492364, 2015). "Surprisingly, knockout of RCAN1 in mouse also inhibited tumor growth due to hyperactivated calcineurin and apoptosis of endothelial cells." (PMID 25811856, 2015).
tumor (continued). "Overexpression of RCAN1 by adenovirus in vivo suppressed xenografted tumor growth in severe combined immunodeficiency (SCID) mouse model." (PMID 26492364, 2015). "Matings were performed to produce Ts65Dn/Rcan1+/+/− mice, which exhibit significantly abrogated tumor protection along with increased microvessel density, demonstrating that Rcan1 overexpression plays an important role in these processes." (PMID 22461792, 2012). "Recently overexpression of the Hsa21 gene, regulator of calcineurin (RCAN1), was shown to be sufficient to suppress tumour growth by attenuating angiogenesis via the regulation of vascular endothelial growth factor (VEGF) signaling." (PMID 23554618, 2010). "Notably, silencing RCAN1-4 expression in RCAN1-4pos GBM cells significantly impeded tumor killing by TCR-T cells, which was comparable to the inhibition observed after antibody-mediated blockade of MHC-I." (PMID 41436600, 2026). "Moreover, we found that adult and pediatric GBM, which are distinct tumor types, both expressed RCAN1-4." (PMID 41436600, 2026). "We postulated that this approach may minimize the off-target effects of RCAN1-4-targeted TCR-T cells while maximizing tumor penetration of the TCR-T cells." (PMID 41436600, 2026). "Having demonstrated specific recognition of the RCAN1-422-32 epitope and tumor cell lysis of RCAN1-4pos human GBM cells by TCRC3-1- and TCRC6-2-engineered human T cells (TCR-TC3-1 and TCR-TC6-2, respectively), we next aimed to assess their therapeutic potential in vivo." (PMID 41436600, 2026). "Similarly, in the current work, we tested the intracranial tumor injection of RCAN1-4-targeted TCR-T cells and demonstrated its efficacy." (PMID 41436600, 2026). "Finally, we assessed the expression of these distinct RCAN1 isoforms across tumor types and molecular subtypes in adult and pediatric patients and normal tissues." (PMID 41436600, 2026). "The ESR1-DAB2 cistromic-transcriptomic overlap revealed enrichment of RCAN1, which has an isoform (RCAN1.4) that has been associated with tumor suppression in one study, as well as an upstream negative regulator of Myc-1, FILNC1." (PMID 39207954, 2024). "In this study, we found that downregulation of RCAN1 had a tumor-promoting effect on ESCC cells and RCAN1.2 mRNA level of tumor tissue may be as predictor for ESCC postoperative prognosis." (PMID 37576400, 2023). "Previous studies showed that RCAN1 and its isoforms play a critical role on tumor inhibition." (PMID 37576400, 2023). "In addition, many studies have confirmed that RCAN1 inhibits tumor growth and migration by targeting the CaN/NFAT pathway." (PMID 37507403, 2023). "In addition, a single extra transgenic copy of RCAN1 in RCAN1 transgenic mice is sufficient to significantly suppress tumor growth, which results from resisting tumor angiogenesis via suppression of the calcineurin pathway." (PMID 35717152, 2022). "Several studies have demonstrated that overexpression of RCAN1 in vascular endothelium cells contributes to a tumor protective effect by attenuating tumor angiogenesis mediated by vascular endothelial growth factor (VEGF) via inhibition of the calcineurin pathway." (PMID 33824473, 2021). "The tumor occurrence time was delayed in the RCAN1.1 group compared with GFP control group." (PMID 26492364, 2015). "Interestingly, cells with high RCAN1 protein, residing in region proximal to the slit-like structure, were reminiscent of immune cells, while spindle-shaped tumor cells were stained relatively low for RCAN1." (PMID 25811856, 2015). "Transgenic mice mimicking RCAN1 trisomy showed significant suppression of tumour growth." (PMID 25811856, 2015). "Immunohistochemistry staining further showed apparent induction of COX-2 and RCAN1 in kGPCR-tumor." (PMID 25811856, 2015). "Concerning these two aspects, RCAN1 evaluation may be used in endothelial cell proliferation, tumor angiogenesis and disease states vasculopathic development." (PMID 25713607, 2014).
tumor (continued). "Thus, although RCAN1-4 may have a tumor suppressor function, its role in tumor progression remains incompletely understood, and it may contribute to GBM progression." (PMID 41436600, 2026). "Besides RCAN1 plays a role in the tumor cell proliferation, migration and invasion." (PMID 37576400, 2023). "The expression of TAPBPL, SERPINB9, RCAN1, TMBIM4, JUNB, IL4R, and LY75 is significantly up-regulated in tumor samples with their high expression associated with a poor outcome; the expression of MGST3 is down-regulated in tumor samples with its low expression associated with poor prognosis." (PMID 25133526, 2014). "While RCAN1 is a marker for MES-like GBM cells, its functional role in tumor progression remains conflicting, with reported effects ranging from tumor suppression to the promotion of proliferation and invasion." (PMID 41436600, 2026). "Thus, RCAN1-4 could serve as a targetable tumor antigen for therapy-resistant GBM and GSCs." (PMID 41436600, 2026). "To assess the in vivo degranulation and function of RCAN1-4-specific TCR-T cells, we analyzed tumor-infiltrating lymphocytes by flow cytometry on days 3 and 15 after transfer." (PMID 41436600, 2026). "Adding an anti-human MHC-I antibody inhibited killing and resulted in a similar tumor cytotoxicity ratio between SF10281 and SF10281C/EBPβ/RCAN1-4 pos." (PMID 41436600, 2026). "They further demonstrated that the deletion of one copy of Rcan1 in Ts65n mice reversed the B16F10 tumor growth suppression phenotype at a modest level, suggesting that it acts as a tumor suppressor." (PMID 40333415, 2025). "By inhibiting calcineurin, RCAN1 reduces NFAT activity, leading to decreased angiogenesis and potentially limiting tumor growth." (PMID 40333415, 2025). "The peptides with increased presentation in SK-Mel-28 dr cells derived from EIF4B, FAM20B, LDHB, CYCS, C5orf22, RCAN1 and DIEXF and were recurrently identified in TvHdb in a variety of tumor patients." (PMID 39835134, 2024). "Some tumor-derived exosome (TEX) miRNAs can promote angiogenesis and metastasis of tumors by inhibiting RCAN1." (PMID 35717152, 2022). "Accordingly, higher mRNA levels of RCAN1.4 and RUNX3 were observed in normal tissues than in tumour breast tissues." (PMID 32771023, 2020). "We then quantified the expression of IL-8 and RCAN1, two NFAT-dependent genes, by qRT-PCR using tumor tissues." (PMID 25811856, 2015). "As RCAN1-4 expression reduces over time, the expression of CXCL8 increases to promote tumour cell proliferation." (PMID 19819266, 2009). "By cloning the RCAN1-422-32-reactive T cell receptor (TCR) derived from single-cell sequencing, we constructed RCAN1-422-32-specific TCR-engineered T cells (TCR-T cells) and validated their efficacy in killing tumor cells in vitro and reducing the tumor burden in vivo." (PMID 41436600, 2026). "However, our results indicated that RCAN1-4 expression was most strikingly increased in aggressive GBM and tended to increase with tumor grade." (PMID 41436600, 2026). "In addition, this study found increased expression of miR-619-5p, decreased expression of RCAN1.4, and increased expression of CD31 in the tumor tissue of NSCLC patients, suggesting their role in tumor promotion and angiogenesis." (PMID 38002256, 2023). "Some of the candidate genes implicated were studied in mice, although single-gene perturbations did not explain all of the angiogenic phenotypes in Ts65Dn mice; overexpression of RCAN1 and DYRK1A were reported to affect proliferation, vascular structures, and tumor allografts." (PMID 35947952, 2022). "RCAN1's inhibition of NF-κB is independent of its inhibition on calcineurin, thus providing a novel mechanism for tumor suppressive effect of RCAN1." (PMID 26492364, 2015). "However, low levels of RCAN1 overexpression, approximately 1.5-fold higher than the native RCAN1 gene, under in vivo conditions do not result in tumor suppression in the absence of HSA21 genes." (PMID 35717152, 2022).
tumor (continued). "However, in a Ts65Dn trisomic background removal of one copy of Rcan1 did not completely abrogate the effect of trisomy on tumour formation, suggesting that other Hsa21 genes also contribute to this phenotype." (PMID 23554618, 2010).
infection (9 papers, 2009 to 2025). The state of being infected such as from the introduction of a foreign agent such as serum, vaccine, antigenic substance or organism. "RCAN1-deficient mice displayed increased mortality following infection with bacterial pathogens, which is associated with higher levels of pro-inflammatory cytokines." (PMID 35204088, 2022). "On the other hand, infection of cells with RCAN1 shRNA resulted in an increase in the expression PROK1-induced IL-8 mRNA (p < 0.05) and protein (p < 0.05) compared to cells infected with NT shRNA." (PMID 19348862, 2009). "This is further supported by our observation that infection of Ishikawa PROKR1 cells with an RCAN1 shRNA lentivirus construct resulted in a significant reduction in the expression of RCAN1-4." (PMID 19348862, 2009). "Conversely, infection of cells with RCAN1-4 lentivirus short hairpin (Sh) RNA which ablates RCAN1-4 protein expression, augmented the PGF2α-FP receptor activation of CXCL8 mRNA (P < 0.01) and protein (P < 0.01) confirming that RCAN1-4 is a negative regulator of CXCL8." (PMID 19819266, 2009). "RCAN1, SLC6A6, RHOB, DUSP, TGM3, and TP53INP2 DEGs, which are related to DNA damage-induced apoptosis, autophagy, the cell cycle, and inflammatory repression, were also upregulated after vPdR-36U infection." (PMID 40006915, 2025). "Lentiviral infection does not modify the effects of histamine on cells, as the Rcan1 pattern expression showed the increase of Rcan1-4 protein resembling that seen in non-transduced cells for both IRES-GFP and Rcan1-IRES-GFP HV-ECs." (PMID 29104573, 2017). "Note that Rcan1, which was only 1.3-fold up in the TZ-infection and therefore did not meet our threshold for inclusion of being at least 1.5-fold up, was just 1.6-fold up in the SPZ-infected samples; this marginal difference is unlikely to be biologically significant." (PMID 28362800, 2017).
neurodegenerative disease (4 papers, 2016 to 2022). A disorder of the central nervous system characterized by gradual and progressive loss of neural tissue and neurologic function. "These include Spon2, Adam19, Arntl, Cdkn1a, Cry2, Per2, Per3, Wee1, Rcan1, Slc41a3, Errfi1, and Bhlhe41, which are related to numerous cardiovascular and degenerative diseases of other organs as well as varying aging processes." (PMID 33668521, 2021). "First, UPS impairment leads to the dysregulation of gene expression by reducing the degradation of transcriptional factors, e.g., NF-κB, HIF-1α, NFAT, etc., which contributes to the dysregulation of neurodegenerative disease-associated proteins, e.g., BACE1, RCAN1, TMP21, etc.." (PMID 31508418, 2019). "In addition, various neurodegenerative disease-associated proteins are degraded via UPS, e.g., BACE1, RCAN1, TMP21, etc.." (PMID 31508418, 2019). "Notably, in that study RCAN1 facilitative activity was switched on by nuclear export of GSK-3β, indicating that targeting the factors involved in this inhibitory mechanism of GSK-3β-mediated NFAT nuclear export may have a therapeutic potential in neurodegenerative diseases." (PMID 27597899, 2016).
cardiovascular diseases (2 papers, 2014 to 2020). "It is desirable to elucidate the RCAN1 function and associate it to cardiovascular diseases in the near future." (PMID 25713607, 2014). "This review tried to explain a possible relation between cardiovascular disease evolution in mammals and the calcium dependent proteins such as RCAN1." (PMID 25713607, 2014).
neurological disease (2 papers, 2019 to 2021). "Assessment of RCAN1 levels in frontal and temporal cortices from our cohort of neurological diseases revealed a significant elevation only in the temporal cortex of both AD and DLB tissue, as compared to controls." (PMID 31263630, 2019). "Further studies are required to investigate the relevance of RCAN1 in AD, and to also interrogate the potential role/interaction of RCAN1 in the context of neurological diseases such as DLB." (PMID 31263630, 2019). "There is a potential point of intersection between the neuropathology/disease pathogenesis present in DS and other neurological diseases such as AD and DLB that centers around the regulation of RCAN1 and potentially the associated endocytic pathways." (PMID 31263630, 2019).
RCAN1 also shares sentences with these, for which no sentence is quoted: hypertrophy (3 papers); Type 2 Diabetes (3); colorectal cancer (2); Insulin resistance (2); Intellectual disability (2); Allergy (1); autism spectrum disorder (1); autoimmune hepatitis (1); bladder urothelial carcinoma (1); breast invasive carcinoma (1); Burkitt lymphoma (1); cerebral infarction (1); Cerebral ischemia (1); cerebrovascular diseases (1); Concentric hypertrophic cardiomyopathy (1); congenital heart disease (1); coronary heart disease (1); corticobasal degeneration (1); Dementia with Lewy Bodies (1); diabetic nephropathy (1); diaphragmatic hernia (1); diffuse large B-cell lymphoma (1); epilepsy (1); esophageal squamous cell carcinoma (1); glaucoma (1); glomerular diseases (1); Greig cephalopolysyndactyly syndrome (1); heart disease (1); Hepatic fibrosis (1); Hypercholesterolemia (1).
A further 29 diseases each share a sentence with RCAN1 in 1 paper.